CD47 (CD47 molecule)
Diseases named in the same sentence as CD47 in open-access papers (continued):
Sharing a sentence is not in itself a finding about the gene and the disease.
breast carcinoma (continued). "Studies of malignancies such as leukemia, non-Hodgkin’s lymphoma, bladder cancer, and breast cancer have revealed elevated CD47 levels in tumor cells, with high CD47 expression correlating with poor clinical prognosis." (PMID 38273373, 2024). "This indicates that SIRPα-Fc has CD47-mediated agonist activities in breast cancer stem cells affecting proliferation and metastasis pathways that differ from those of CC-90002." (PMID 38495618, 2024). "Chemotherapy with carboplatin, doxorubicin, gemcitabine, or paclitaxel induces enrichment of CD47+CD73+PDL1+ immune evasive breast cancer cells." (PMID 39002018, 2024). "CD47 × PD‐L1 BisAb successfully controlled tumor growth in an orthotopic model of breast cancer and akin to observations in other models, induced the influx of intratumoral macrophages, monocytes and neutrophils." (PMID 39584189, 2024). "Currently, five products targeting the CD47-SIRPα signaling pathway are undergoing various clinical trials for breast cancer treatment." (PMID 39040441, 2024). "CD8+ T cell populations were tracked upon CD47 × PD‐L1 BisAb treatment in an orthotopic model of murine breast cancer where anti‐tumor immunity is mediated by CD8+ T cells." (PMID 39584189, 2024). "CD47 is a transmembrane protein widely expressed but often overexpressed in various tumor types including breast cancer." (PMID 37063284, 2023). "CD47 is a key mediator of immune evasion and epithelial to mesenchymal transition in breast cancer and its high expression is related to worse disease-free survival." (PMID 37685859, 2023). "In liver and breast cancer cells, TNFα induces CD47 expression through the transcriptional regulator, NF-κB." (PMID 37958404, 2023). "In translational studies, analysis of datasets derived from breast cancer patients also revealed that high CD47 mRNA expression levels are correlated with mortality and poor prognosis of patients." (PMID 37063284, 2023). "Here, we found a strong association between overexpression of CD47 on tumor cells and high levels of all TIL subsets in breast cancers, supporting a link between CD47 and the innate immune system." (PMID 36598153, 2023). "Interactions between CD47 and αvβ3 enhanced binding of ovarian and breast cancer cells and spreading of melanoma cells on vitronectin-coated substrates, as well as chemotaxis of prostate cancer and melanoma cells towards collagen." (PMID 37958404, 2023). "We highlight two examples of previously unannotated cancer-cell-specific enhancers of ANXA2 and PRDX4 gene expression and show evidence for super-enhancer regulation of LAMB3 and CD47 in male breast cancer cells." (PMID 37685859, 2023). "Correspondingly, the response to trastuzumab therapy in breast cancer patients appears related to CD47 expression of the cancer cell." (PMID 37063284, 2023). "Subsequently, we assessed the ability of NP/R848/siCD47 to downregulate CD47 expression in mouse breast cancer cells." (PMID 37063284, 2023). "Namely, a collection of particular SEs responsible for CD47 expression were found in breast cancer cell lines (HER2 or ER+ PR+) and breast tumors (ER+ PR+)." (PMID 37190100, 2023). "Metformin has also been identified as a CD47 inhibitor in vitro, with breast cancer cells treated with 10 mM metformin exhibiting a 50% decrease in CD47 mRNA levels." (PMID 37484024, 2023). "To determine the clinical significance of Kaiso with the THBS1/CD47/SIRPA signaling axis in breast cancer patients, we analyzed both the TCGA gene expression and protein dataset." (PMID 37190208, 2023). "Only a few studies report direct evidence of any correlation between the expression of CD47 and prognosis in breast cancer." (PMID 36598153, 2023). "Within our list of 61 upregulated male versus female breast cancer genes linked to cancer-specific enhancers, we identified at least two super-enhancers; one linked to LAMB3 and the other to CD47." (PMID 37685859, 2023).
breast carcinoma (continued). "In a study with breast cancer patients, Papadaki demonstrated that CTCs CD47+ can be found in initial, recurrent, and metastatic disease (p = 0.036), being more frequently observed in patients with recurrent and metastatic disease (p = 0.009)." (PMID 37569332, 2023). "The expression of CD47 has been reported in many tumors such as breast cancer, thyroid cancer, and colorectal cancer." (PMID 37171006, 2023). "For instance, the blood-derived exosomes with a high level of CD47+ were recognized as a screening indicator for the breast cancer." (PMID 37188263, 2023). "The combined effect of DC stimulation by the virus and blockage of CD47-SIRPα signalling resulted in increased survival time in breast cancer induced mice from 16 days to 39 days and a significant reduction in the tumour volume." (PMID 36851335, 2023). "In the MCF7 breast cancer cell line, CD47 increases gene transcription through NF-κB signaling, and blocking TNFαsignaling can inhibit CD47 expression." (PMID 37542283, 2023). "Interference with CD47–SIRPα interactions by antagonistic antibodies or CD47 knockdown obviously enhances the in vitro killing of trastuzumab-treated Her-2+ breast cancer cells by phagocytes." (PMID 37063284, 2023). "Previous reports suggest that high expression of CD47‐SIRPα in the bone marrow and peripheral blood predicts recurrence in breast cancers, and increased CD47 in breast stem cells inhibits phagocytosis." (PMID 36598153, 2023). "It has been reported that HIF-1 directly activated transcription of the CD47 gene in hypoxic breast cancer cells." (PMID 37063284, 2023). "Recent comprehensive analysis of CTCs in breast cancer confirms similar patterns of PD-L1 and CD47 expression as seen in lung cancer." (PMID 38077355, 2023). "In this work, urinary exosomes (UEs) with high expression of CD9 and CD47 were extracted from breast cancer patients by a non−invasive method." (PMID 36004889, 2022). "At the transcriptional level, more understanding about the regulation of CD47 expression in breast cancer has been described." (PMID 35860564, 2022). "first reported CD47 as a prognosis biomarker of breast cancer; compared with controls, breast cancer patients have higher CD47 mRNA, and the high CD47 expression in bone marrow were correlated with poor survival." (PMID 35860564, 2022). "In a pre-clinical model of HER2+ breast cancer, a combination of a CD47 mAb and trastuzumab was also found to successfully augment macrophage-mediated phagocytosis." (PMID 35865547, 2022). "On the other hand, HIF-1α directly activates transcription of CD47 gene in hypoxic breast cancer cells." (PMID 36014432, 2022). "In the current study, we successfully engineered 231‐exo, an MBA‐DM‐231 breast cancer cell‐derived exosome with a commonly used chemotherapeutic drug, cisplatin and anti‐CD47 antibody." (PMID 36054073, 2022). "Blocking both CD47 and TAG-72 with CAR-T cells was associated with increased levels of macrophage-inflammatory protein (MIP)-1α and MIP-1β chemotactic factors in breast cancers, indicating functionality of the CD47 receptor in this model." (PMID 35211124, 2022). "In breast cancer, anti-CD47 antibody mediates direct apoptosis of tumor cells, involving the regulation of cAMP levels via heterotrimeric Gi with subsequent effects mediated by PKA." (PMID 35860564, 2022). "CD47 blockade combined with trastuzumab eradicates HER2-positive breast cancer cells while also overcoming trastuzumab resistance." (PMID 36303138, 2022). "The number of breast CSCs decreases upon inhibition of CD47 expression which is resulting in increased phagocytosis of breast cancer cell." (PMID 36014432, 2022). "It has been shown that CD47 overexpression in most solid tumours, including breast cancer, non-small cell lung cancer and gastric cancer, is associated with poor prognosis." (PMID 35694254, 2022).
breast carcinoma (continued). "We previously showed that in human breast cancer cells HIF-dependent expression of CD47, CD73, and PDL1 inhibited the ability of both the innate and adaptive immune systems to kill cancer cells." (PMID 35499076, 2022). "Currently, CD47 is an attractive target for the development of new anti-cancer therapeutics, including options against breast cancer." (PMID 35860564, 2022). "Immune checkpoint blockade holds great promise in tumor‐targeted therapy, and CD47 blockade as one immune therapy is undergoing various preclinical studies and clinical trials to demonstrate its safety and efficacy in breast cancer." (PMID 35860564, 2022). "Metformin represses CD47 gene expression in a miRNA-708-dependent manner to allow macrophage phagocytosis of breast cancer stem cells." (PMID 35631452, 2022). "came to a similar conclusion that the knockdown of CD47 expression increased macrophage-mediated cytotoxicity toward breast cancer cells, and the level of CD47 was negatively correlated with the degree of phagocytosis." (PMID 35860564, 2022). "Breast cancer‐associated HER2 and lymphoma‐related CD47 exhibit a “please don't eat me” signal to macrophages." (PMID 35573135, 2022). "A recent study reported that the CD47 level in EXOs from the plasma of breast cancer patients was higher than in healthy controls." (PMID 35845399, 2022). "An analysis of 353 breast cancer patients and a public data set showed that the high CD47 mRNA levels were correlated with poor-prognosis molecular subtypes (basal, Her2/Neu+) and adverse clinicopathological parameters (high-grade, ER-, PR-)." (PMID 35860564, 2022). "The authors also reported that HIF-1 raised CD47 expression to promote breast cancer cells escape from macrophage phagocytosis." (PMID 35860564, 2022). "In both solid tumors and hematological malignancies, such as ovarian cancer, breast cancer, multiple myeloma and Non-Hodgkin lymphoma (NHL), elevated CD47 expression is associated with a poor prognosis." (PMID 35865547, 2022). "Hypoxia-inducible factor 1 (HIF-1) binds to the CD47 promoter, activating gene transcription and increasing CD47 expression in breast cancer cells." (PMID 35860564, 2022). "In preclinical models of HER2+ breast cancer, CD47 blockade significantly increased ADCP and enhanced trastuzumab therapeutic outcomes." (PMID 35860564, 2022). "Normal cells regularly express CD47, with higher expression being found in tumor cells such as breast cancer, hepatocellular carcinoma, ovarian clear cell carcinoma, and melanoma." (PMID 36358792, 2022). "In this review, we summarized different therapeutic mechanisms targeting CD47 and its prognostic role and therapeutic value in breast cancer." (PMID 35860564, 2022). "CD47 is overexpressed in various cancer types, including breast cancer, acute myeloid leukemia (AML) and chronic myeloid leukemia (CML), leiomyosarcoma, and head and neck squamous cell carcinoma." (PMID 36171566, 2022). "Recently, the same research team has demonstrated that co-expression of CD47 and GRP78 associated with a poor outcome in breast cancer patients." (PMID 35127545, 2022). "CD47 is directly regulated by HIF-1 in hypoxic breast cancer cells and plays an immune escape through the CD47-SIRPα axis." (PMID 36226050, 2022). "In conclusion, CD47 is a novel attractive target for the treatment of breast cancer, which functions as ‘don’t eat me’ signal to assist cancer cells to escape immunosurveillance." (PMID 35860564, 2022). "Breast cancer cells expressing CD47, an immune checkpoint molecule that interacts with macrophages expressing LGALS9, were reported to correlate with poor clinical outcomes." (PMID 36148946, 2022). "Similar results can be found in breast cancer, as the treatment with of an anti-CD47 antibody promotes the effect of doxorubicin chemotherapy, inhibiting the growth of tumor cells significantly." (PMID 36358792, 2022).
breast carcinoma (continued). "The overexpression of CD47 has been reported in various types of cancers, such as non-small cell lung cancer, breast cancer, stomach cancer, and non-Hodgkin lymphoma and has been associated with an adverse prognosis." (PMID 33917794, 2021). "CD47 is also expressed on various cancer cell types, including breast cancer cells, and behaves as a “don’t eat me signal”." (PMID 34439212, 2021). "A significant reduction in CD47 expression in circulating exosomes was observed in breast cancer patients." (PMID 34659224, 2021). "The breast cancer stem cell markers CD47, CD44, CD24, and CD133 have all been extensively studied and reviewed." (PMID 34205080, 2021). "In response to mitoxantrone, anti-CD47 antibody significantly enhances antitumor activity in breast cancer cells." (PMID 34512146, 2021). "Hypoxia-inducible factor 1 regulates CD47 expression in breast cancer cells to promote evasion of phagocytosis and maintenance of cancer stem cells." (PMID 34717705, 2021). "TSP1 and CD47 were identified on the surface of EVs released by myeloid-derived suppressor cells (MDSCs) induced in mice by implanted 4T1 mouse mammary carcinoma." (PMID 33925464, 2021). "In the basal-like and HER2+ breast cancer subtypes, the expression of the CD47-immune signature predicted favorable outcome, correlated with the presence of tumor immune infiltrates, and with gene expression signatures of T cell activation." (PMID 33917174, 2021). "Elevated CD47 expression is reported in HER2 positive breast cancer HCC1954 and MCF7 cells and NF-κB and PPARα are detected in the super-enhancer of CD4752." (PMID 32929084, 2020). "More recently CD47 was found to have another co-expression model in breast cancer in which the glucose-regulated protein 78 (GRP78) was linked with CD47 function." (PMID 32929084, 2020). "Metformin modulates the following axes: miR-miR-708/CD47 in breast cancer, miR-27b/ENPP1 in breast cancer, 26a/EZH2 in pancreatic cancer, and blocks TGFβ1-induced upregulation of miR-181a and downregulation of miR-96 in breast cancer." (PMID 32512882, 2020). "A study shows that blocking CD47 can enhance the antitumor effect of trastuzumab in breast cancer and that the expression of tumor-related cytokine CD47 was inversely correlated with survival in breast cancer patients with HER2+." (PMID 32733941, 2020). "Here, we report that CD47-mediated anti-phagocytosis is concurrently upregulated with HER2 in radioresistant breast cancer (BC) cells and RT-treated mouse syngeneic BC." (PMID 32929084, 2020). "Another study found that blocking of CD47 on 4T1 mouse breast cancer cells prior to tail vein injection significantly reduced the number of lung metastases in mice." (PMID 32984308, 2020). "In breast cancer and pancreatic adenocarcinoma, hypoxia has been shown to positively regulate the expression of CD47, leading to cancer cell escape from phagocytosis mediated by macrophages." (PMID 33330037, 2020). "To test the prophagocytic effect of cisplatin in other solid cancers, we next investigated if the combination of cisplatin and anti-CD47 had better efficacy than each treatment used alone in breast cancer model." (PMID 32198351, 2020). "Exosomal proteins including fibronectin, surviving, HER2, periostin, and CD47 have been used as markers for the diagnosis of breast cancer." (PMID 33282730, 2020). "Altogether, these results suggest that CD47 and HER2 are mutually activated at the transcriptional level contributing to the aggressive phenotype of radiation-resistant breast cancer cells via HER2–NF-κB-controlled CD47 promoter activation." (PMID 32929084, 2020). "In breast cancer, evidence has been reported that hypoxia positively regulates the expression of CD47 by showing that the expression of CD47 is positively correlated with the expression of HIF-1α downstream target genes." (PMID 31540045, 2019). "The results presented here also demonstrate that CD47 regulates the drug resistance of the stem cells in breast cancer." (PMID 31273952, 2019).
breast carcinoma (continued). "Of 217 breast cancer tissues, 140 (64.5%) showed high expression of CD47 protein and 77 (35.5%) showed low expression." (PMID 31528120, 2019). "Our results were consistent with previous study indicating that CD47 was regulated by sets of pro-inflammatory super-enhancers in breast cancer, diffuse large B-cell lymphoma and acute lymphoblastic leukemia." (PMID 31829270, 2019). "Both of the CD47 and CD68 expression were significantly higher in breast cancer tissues (P < 0.001), and associated with multiple clinicopathological parameters in breast cancer (P < 0.05)." (PMID 31528120, 2019). "Two hundred seventeen cases of breast cancer tissues and 40 cases of benign breast lesions were collected for immunohistochemical staining of CD47 and CD68." (PMID 31528120, 2019). "In accordance with this, we found the frequent presence of CD68-labeled TAMs around or in the nest of breast cancer with high expression of CD47." (PMID 31528120, 2019). "In this study, 217 cases of primary invasive breast cancer tissues were collected to detect the expression of CD47, and we revealed the direct evidence that CD47 was overexpressed in breast cancer solid tumors." (PMID 31528120, 2019). "In this study, we evaluated the expression of CD47 in 217 solid breast cancer tissues and 40 benign breast lesions." (PMID 31528120, 2019). "On the other hand, CD47 is essential for self‐renewal, tumour initiation and chemoresistance of BCSCs, and correlates with the prognosis of breast cancer patients." (PMID 31273952, 2019). "In this study, the expression of CD68 was positively correlated with that of CD47, and CD47highCD68high was found in 49.8% of breast cancer patients." (PMID 31528120, 2019). "CD47 induced the production of stem cells and phagocytosis of macrophages, leading to chemoresistance of breast cancer." (PMID 31273952, 2019). "To identify the target of miR‐708 that mediates the generation of stem cells in breast cancer, we searched for predicted target genes using miRanda and found the mirSVR score of CD47 ranked near the top in the obtained list." (PMID 31273952, 2019). "CD47 protein was mainly localized in the cytoplasm or cell membrane of tumor cells in breast cancer tissues, while the immunoreactivity for CD47 in benign breast lesions was negative or weakly positive in the cytoplasm." (PMID 31528120, 2019). "The expression of CD47 was significantly higher in breast cancer tissues (χ2 = 16.652, P < 0.001) as determined by Chi-square test." (PMID 31528120, 2019). "Cancerous cells, including those of acute myeloid leukemia, bladder cancer, and breast cancer, have been found to overexpress CD47 as a means to evade the immune system." (PMID 30463284, 2018). "This study elucidated another mechanism by which breast cancer escapes immune surveillance, which involves the upregulation of CD47 by SE, which inhibits phagocytosis signaling." (PMID 30213113, 2018). "These FACS results clearly support the idea of utilizing CD47 SERS NPs as imaging contrast agents in these breast cancer cell lines." (PMID 30463284, 2018). "In summary, all seven of the breast cancer cell lines we investigated, including three triple-negative lines, showed overexpression of CD47." (PMID 30463284, 2018). "In a mouse xenograft model of human breast cancer, topical application of CD47-targeted nanoparticles to excised normal and cancer tissue revealed increased binding of CD47-targeted nanoparticles on tumor relative to normal adjacent tissue." (PMID 30463284, 2018). "The isotype IgG-labeled SERS NPs showed significantly less binding (p < 0.01) in the breast cancer cell lines than CD47-targeted SERS NPs." (PMID 30463284, 2018). "They observed that the CD47 blockade sensitized cancer cells to phagocytosis, particularly in breast cancer cells with Mesenchymal features." (PMID 30301213, 2018).